FLT1 (fms related receptor tyrosine kinase 1)
Description:
Tyrosine-protein kinase that acts as a cell-surface receptor for VEGFA, VEGFB and PGF, and plays an essential role in the development of embryonic vasculature, the regulation of angiogenesis, cell survival, cell migration, macrophage function, chemotaxis, and cancer cell invasion. Acts as a positive regulator of postnatal retinal hyaloid vessel regression (By similarity). May play an essential role as a negative regulator of embryonic angiogenesis by inhibiting excessive proliferation of endothelial cells. Can promote endothelial cell proliferation, survival and angiogenesis in adulthood. Its function in promoting cell proliferation seems to be cell-type specific. Promotes PGF-mediated proliferation of endothelial cells, proliferation of some types of cancer cells, but does not promote proliferation of normal fibroblasts (in vitro). Has very high affinity for VEGFA and relatively low protein kinase activity; may function as a negative regulator of VEGFA signaling by limiting the amount of free VEGFA and preventing its binding to KDR. Modulates KDR signaling by forming heterodimers with KDR. Ligand binding leads to the activation of several signaling cascades. Activation of PLCG leads to the production of the cellular signaling molecules diacylglycerol and inositol 1,4,5-trisphosphate and the activation of protein kinase C. Mediates phosphorylation of PIK3R1, the regulatory subunit of phosphatidylinositol 3-kinase, leading to activation of phosphatidylinositol kinase and the downstream signaling pathway. Mediates activation of MAPK1/ERK2, MAPK3/ERK1 and the MAP kinase signaling pathway, as well as of the AKT1 signaling pathway. Phosphorylates SRC and YES1, and may also phosphorylate CBL. Promotes phosphorylation of AKT1 at 'Ser-473'. Promotes phosphorylation of PTK2/FAK1. [Isoform 1]: Phosphorylates PLCG. [Isoform 2]: May function as decoy receptor for VEGFA. [Isoform 3]: May function as decoy receptor for VEGFA. [Isoform 4]: May function as decoy receptor for VEGFA. [Isoform 7]: Has a truncated kinase domain; it increases phosphorylation of SRC at 'Tyr-418' by unknown means and promotes tumor cell invasion.
Synonyms: VEGFR-1; FLT-1; FLT; VEGFR1
Tractability: Small molecule: an approved drug acts on it; a structure with a bound ligand is known; a high-quality ligand is known; it belongs to a druggable protein family. Antibody: a drug acting on it is in phase 2 or 3 trials; UniProt places it where antibodies can reach, with high confidence; its Gene Ontology location is reachable by antibodies, with high confidence; UniProt predicts a signal peptide or a membrane-spanning region; the Human Protein Atlas places it where antibodies can reach. PROTAC: it is named in the literature on targeted protein degradation; UniProt records ubiquitination sites on it; ubiquitination databases record sites on it; a small molecule that binds it is known. Other modalities: a drug acting on it is in phase 2 or 3 trials.
Target class: Tyrosine protein kinase VEGFR family; Enzyme; TK protein kinase group; Protein Kinase; Kinase
Chemical probes: TIVOZANIB
Safety:
Unwanted effects reported when the protein is acted on. In parentheses: how it was acted on, where the effect was seen, and who reports it.
brain natriuretic peptide increase (inhibition; metabolic/endocrine; source: Brennan et al. (2024))
Haemorrhage (inhibition; cardiovascular; source: Brennan et al. (2024))
hypertension (inhibition; cardiovascular; source: Brennan et al. (2024))
hyponatraemia (inhibition; metabolism; source: Brennan et al. (2024))
impaired healing (inhibition; source: Brennan et al. (2024))
Increased, Developmental Defects (inhibition; source: AOP-Wiki)
heart disease (cardiovascular system; source: Force et al. (2011))
Gene: Protein-coding gene on chromosome 13 (28,300,346 to 28,495,145, reverse strand). Ensembl gene ENSG00000102755.
Subcellular location: Cell membrane (Isoform 1); Endosome; Secreted (Isoform 2); Secreted (Isoform 3); Secreted (Isoform 4); Cytoplasm (Isoform 5); Cytoplasm (Isoform 6); Cytoplasm (Isoform 7)
Subcellular location (Human Protein Atlas): Plasma membrane; Actin filaments; Cytosol; Predicted to be secreted
Pathways (Reactome):
Signal Transduction: Neuropilin interactions with VEGF and VEGFR; VEGF binds to VEGFR leading to receptor dimerization
Gene Ontology:
Molecular function: growth factor binding; placental growth factor receptor activity; protein binding; protein tyrosine kinase activity; vascular endothelial growth factor receptor activity; transmembrane receptor protein tyrosine kinase activity; ATP binding; protein kinase activity
Biological process: cell migration; cellular response to vascular endothelial growth factor stimulus; monocyte chemotaxis; negative regulation of vascular endothelial cell proliferation; peptidyl-tyrosine phosphorylation; positive regulation of angiogenesis; positive regulation of cell migration; positive regulation of MAP kinase activity; positive regulation of MAPK cascade; positive regulation of phosphatidylinositol 3-kinase/protein kinase B signal transduction; protein autophosphorylation; vascular endothelial growth factor receptor signaling pathway; vascular endothelial growth factor receptor-1 signaling pathway; blood vessel morphogenesis; cell surface receptor protein tyrosine kinase signaling pathway; embryonic morphogenesis; hyaloid vascular plexus regression; positive regulation of cell population proliferation; sprouting angiogenesis; positive regulation of developmental process; regulation of cell population proliferation; vascular endothelial growth factor signaling pathway
Cellular component: focal adhesion; plasma membrane; receptor complex; extracellular region; cytoplasm; endosome
Genetic constraint (gnomAD): Loss-of-function variants: 32 observed, 113.51 expected, observed/expected ratio (o/e) 0.28, 90% interval 0.21 to 0.38. The upper end of that interval is the gene's LOEUF score, 0.38, which puts it in group 1 of 6, group 1 being the genes least tolerant of losing a copy. Missense variants: 1,127 observed, 1,433.8 expected, observed/expected ratio (o/e) 0.79, 90% interval 0.75 to 0.83. Synonymous variants: 522 observed, 523.37 expected, observed/expected ratio (o/e) 1, 90% interval 0.93 to 1.07.
Homologues: Orthologues: chimpanzee FLT1 (99% identical), macaque FLT1 (98% identical), dog FLT1 (90% identical), pig FLT1 (87% identical), rabbit FLT1 (84% identical), rat Flt1 (82% identical), mouse Flt1 (82% identical), guinea pig FLT1 (80% identical), zebrafish flt1 (48% identical). Paralogues in human: KDR (44% identical), FLT4 (40% identical), PDGFRA (24% identical), PDGFRB (22% identical), KIT (22% identical), CSF1R (21% identical), FGFR1 (18% identical), FGFR2 (18% identical), FLT3 (18% identical), FGFR3 (17% identical), FGFR4 (17% identical), IGF1R (15% identical), and 41 more.
Diseases named in the same sentence as FLT1 in open-access papers:
FLT1 is named in the same sentence as 375 diseases in open-access papers, as found by Europe PMC text mining. Sharing a sentence is not in itself a finding about the gene and the disease. The quoted sentences say what the papers report.
preeclampsia (289 papers, 2008 to 2026). Preeclampsia is a hypertensive disorder of pregnancy that is characterized by new-onset hypertension with proteinuria presenting after 20 weeks of gestation, and depending on mild or severe forms may initially present with severe headache, visual disturbances, and hyperreflexia. "Soluble FLT1 has been associated with preeclampsia (PE), which is a severe complication affecting 5–7% of pregnancies worldwide with high morbidity and mortality." (PMID 40632597, 2025). "Previous studies have also identified the C/T variant rs4769613, located near FLT1, as a strong risk factor for preeclampsia." (PMID 39194706, 2024). "The meta-analysis results showed that the maternal polymorphism FLT1 rs4769613 was significantly associated with preeclampsia risk in the allelic model (additive model, OR 0.92, 95% CI 0.86 to 0.98, I2 = 54.2%, n = 5)." (PMID 39194706, 2024). "The relationships between maternal and fetal variants on the development of preeclampsia (PE) is undeniable because FLT1 plays a crucial role in placentation progression." (PMID 39194706, 2024). "A significant association was observed between FLT1 rs4769613 and preeclampsia in both dominant and recessive models for mothers and fetuses." (PMID 39194706, 2024). "Our meta-analysis revealed that both the maternal and fetal polymorphisms, FLT1 rs4769613, were significantly associated with the risk of preeclampsia." (PMID 39194706, 2024). "Encouragingly, essential differentially expressed genes implicated in Preeclampsia, such as FLT-1, Endoglin, and ADAMTS, were predicted targets of the differentially expressed microRNAs in our study." (PMID 38628314, 2024). "The results of this study demonstrate that the FLT1 rs4769513 polymorphism in both the mother and fetus affects the likelihood of preeclampsia." (PMID 39194706, 2024). "In FLT1, variant rs4769613, positioned on chromosome 13 (GRCh38.p14), has been linked to an increased risk of preeclampsia (PE) in the placenta." (PMID 39194706, 2024). "FMS-associated tyrosine kinase 1 pseudogene 1 (FLT1P1) and FLT1 have been shown to regulate trophoblast proliferation and angiogenesis in preeclampsia." (PMID 37389124, 2023). "Our findings suggest that LEP, SASH1, RAB6C, and FLT1 can be used as placental markers for preeclampsia and they are associated with various immune cells." (PMID 37389124, 2023). "Overexpression of FLT1 in placental tissue, detection of a soluble isoform of FLT1 in maternal circulation, and fetal genetic variants near FLT165 have implicated FLT1 in preeclampsia etiology." (PMID 36914823, 2023). "Characteristic genes, LEP, SASH1, RAB6C, and FLT1 can be used as diagnostic and therapeutic targets for preeclampsia, and they are associated with immune cell infiltration." (PMID 37389124, 2023). "Cellular composition mediated a substantial proportion of the association between preeclampsia and FLT1 (37.8%, 95% CI [27.5%, 48.8%]), LEP (34.5%, 95% CI [26.0%, 44.9%]), and ENG (34.5%, 95% CI [25.0%, 45.3%]) overexpression." (PMID 36914823, 2023). "Although GWAS associations are understudied in pregnancy relative to other disease states, the most robust GWAS SNP association for preeclampsia, rs4769613 (replicated in two studies), maps to the FLT1 enhancer region (enhancer number 22)." (PMID 37694817, 2023). "High levels of flt-1 are associated with glomerular endotheliosis, proteinuria, and hypertension in non-pregnant and pregnant rats, which are important features of preeclampsia." (PMID 36420291, 2022). "In turn, it was found that the FLT1 rs722503 polymorphism correlated with an increased susceptibility to preeclampsia in a dominant model, designed with regards to Iranian women." (PMID 34828331, 2021). "Regarding FLT1 rs722503, the T allele was previously reported to be associated with an increased risk of preeclampsia in populations of Iranian and white pregnant women." (PMID 34828331, 2021).
preeclampsia (continued). "MMPs are involved in proteolytic cleavage of cell surface molecules such as Flt1 and Eng that are distinctly associated as antiangiogenic mediators of preeclampsia." (PMID 34195300, 2021). "•Partial loss of heme oxygenase-1 under high soluble Flt-1 causes severe preeclampsia compared to high sFlt-1 alone." (PMID 33137710, 2021). "The fetal preeclampsia FLT1 variant was tested using the individual’s own birth weight (N = 236,507) while the maternal preeclampsia variants were tested using the reported birth weight of the female participant’s first child (N = 178,241)." (PMID 33239696, 2020). "Recently, a genome-wide association study of 4380 cases of preeclampsia and 310,238 controls identified that a variant in the foetal genome near the locus of fms-like tyrosine kinase-1 (Flt-1) is implicated in the development of preeclampsia." (PMID 31590294, 2019). "Trisomy 13 (chromosome 13 contains the FLT1 locus) is associated with increased maternal levels of sFlt1 and a high risk of preeclampsia." (PMID 31480243, 2019). "Recently, a large clinical genome-wide association study revealed significant association between single-nucleotide polymorphism near the FLT1 locus (rs4769613) on chromosome 13 in the fetal genome and the development of preeclampsia." (PMID 31480243, 2019). "The first genome wide association study of offspring from preeclamptic pregnancies reported that common variants near FLT1 on chromosome 13 were associated with preeclampsia." (PMID 30483272, 2018). "In this mini-review we explore the immunogenetic role of FLT1 in preeclampsia and selected genetic studies implicating loss of immune tolerance in early pregnancy or late pregnancy inflammation in preeclampsia." (PMID 30483272, 2018). "The truncated/secreted form of Flt-1 (sFlt-1) has also been implicated in the pathogenesis of preeclampsia." (PMID 28790977, 2017). "We also conducted an analysis of ENCODE Chip Seq data to infer common transcription regulatory networks of selected genes (such as TTD genes and GTF2E1) and gene regulators (such as EGFR, ATF3, and FLT1) implicated in preeclampsia." (PMID 24885447, 2014). "Soluble Flt1 is an alternatively spliced gene product of Flt1, which has been implicated in pathologies associated with preeclampsia and also during physiological functions such as blood vessel sprouting." (PMID 22962618, 2012). "Severe preeclampsia is associated with increased neutrophil activation and elevated serum soluble endoglin (sEng) and soluble Flt-1 (sFlt-1) in the maternal circulation." (PMID 22398973, 2012). "As trophoblast cells, which also express Flt-1, are fetal of origin, the role of fetal Flt-1 (TG)n polymorphism needs also to be examined in the risk of preeclampsia." (PMID 18631405, 2008). "This is the first study to characterize the dinucleotide repeat polymorphism of the Flt-1 gene in patients with preeclampsia." (PMID 18631405, 2008). "The aim of this study was to investigate the relationship between preeclampsia and a dinucleotide (threonine-glycine; TG)n repeat polymorphism in the 3' non-coding region of the Flt-1 gene." (PMID 18631405, 2008). "A genome-wide study linked a fetal genome single-nucleotide polymorphism near FLT1 to preeclampsia." (PMID 40703703, 2025). "Indeed, subsequent large genome-wide association studies have revealed further corroborating evidence that fetal variants in the FLT1 locus are robustly associated with preeclampsia." (PMID 39087479, 2024). "The meta-analysis results reveal that the fetal polymorphism FLT1 rs4769613 is significantly associated with an increased risk of preeclampsia in the allelic model, with an odds ratio of 0.83, a 95% confidence interval of 0.76 to 0.90, and an I2 of 51.1% (n = 5)." (PMID 39194706, 2024).
preeclampsia (continued). "In the model without interaction, 37.8% (95% CI [27.5%, 48.8%]) of the 1.05 (95% CI [0.89, 1.21]) log2 signal intensity increase in the association between preeclampsia and FLT1 expression was attributable to differences in placental cell composition between preeclampsia cases and controls." (PMID 36914823, 2023). "The influence of FLT1 gene polymorphisms is often studied in preeclampsia." (PMID 36901702, 2023). "Likewise, FLT1 (encoding vascular endothelial growth factor receptor 1), another gene linked to many enhancers, is dysregulated in preeclampsia." (PMID 37694817, 2023). "Variants in the fetal genome near FLT1 have been associated with preeclampsia, a condition of pregnant women presenting with hypertension and damage to the liver and kidneys, whose underlying mechanism involves abnormal formation of blood vessels in the placenta." (PMID 37131961, 2023). "In contrast, FLT1 mRNA levels (sFLT1 is a splice variant of FLT1, the increase of which is associated consistently with preeclampsia) were 1.87-fold higher in women with preeclampsia (P = 0.001)." (PMID 29803833, 2018). "Indeed, the clinical significance of soluble Flt-1 in kidney diseases was first reported in association with preeclampsia." (PMID 29937525, 2018). "Recently, in a large genome wide association study of preeclampsia a first robust association in the fetal genome was found in the common variant near Fms related tyrosine kinase gene (FLT1) encoding anti-angiogenic factor Fms-like tyrosine kinase 1 (FLT1)." (PMID 30483272, 2018). "In contrast, soluble FLT1 (a protein with an established association with preeclampsia) mRNA was increased in placental tissue (mean difference, 34.9%; 95% CI, 16.6 to 53.1; P = 0.001), and circulating concentrations were 16.8-fold higher among the preeclamptic cohort (P < 0.0001)." (PMID 29803833, 2018). "That Flt-1 is present on EVs extruded from first trimester placentae supports the idea that vesicle-associated Flt-1 may potentially contribute to the early pathogenesis of preeclampsia from the first trimester onward." (PMID 28790977, 2017). "Since Flt-1/sFlt-1 has previously been implicated in the pathogenesis of preeclampsia, whether Flt-1 is present in placental EVs at different gestations was investigated by western blotting." (PMID 28790977, 2017). "The hypothesis that preeclampsia might arise because of the loss of VEGF activity as a result of the “increase in the levels of endogenous soluble Flt-1 that may antagonize the beneficial effects of VEGF” was first proposed in a review in 1997." (PMID 24503248, 2014). "The angiogenic imbalance hypothesis proposed that preeclampsia arises due to loss of vascular endothelial growth factor (VEGF) activity as a result of rise in soluble Flt-1 (sFlt-1)." (PMID 22398973, 2012). "In this study, we focused on a d(TG)n repeat polymorphism in the Flt-1 gene which may be associated with preeclampsia in Korean pregnant women." (PMID 18631405, 2008). "Considering the important roles of Flt-1 in pregnancy, functional polymorphisms in the Flt-1 gene may be potentially important as genetic markers for susceptibility to preeclampsia." (PMID 18631405, 2008). "Based on genetic predisposition, this relationship may be strengthened by showing an association between polymorphisms of Flt-1 gene and an increased risk of developing preeclampsia." (PMID 18631405, 2008). "Given the regulatory role of Flt-1 in pregnancy and the presence of a multiallelic polymorphism in the Flt-1 gene, Flt-1 could conceivably be a candidate susceptibility gene in preeclampsia." (PMID 18631405, 2008). "Consequently, positive selection on a genetic variant with capacity to resist placental malaria by increasing sFLT concentration may have influenced FLT1 allele frequencies within the general population enough to introduce a novel risk to preeclampsia." (PMID 30483272, 2018).